WT1 (WT1 transcription factor)
Diseases named in the same sentence as WT1 in open-access papers (continued):
Sharing a sentence is not in itself a finding about the gene and the disease.
heart failure (5 papers, 2013 to 2025). Inability of the heart to pump blood at an adequate rate to meet tissue metabolic requirements. "Complementation of Wt1 null embryos with a human WT1 transgene rescued both embryonic heart defects and midgestational death, confirming that indeed heart failure causes the death of Wt1-deficient embryos." (PMID 34299295, 2021). "It has been noted earlier that the Wilms’ tumor suppressor, Wt1, is required for murine heart development as Wt1 knockout mice have severely hypoplastic hearts and die during mid-gestation, most likely due to heart failure." (PMID 33919406, 2021). "Disruption of Wt1 activity results in developmental abnormalities, and Wt1−/– mice are embryonic lethal at embryonic day 12.5 (E12.5), with heart failure being one of the contributing factors to their early demise." (PMID 26702046, 2015).
Infertility (5 papers, 2013 to 2025). "Some hereditary cancer genes (e.g. BRCA2, FANCM, MLH1, WT1) have been directly linked to human infertility." (PMID 40060932, 2025). "In this cohort, a reasonable genotype–phenotype correlation was detected, as a damaging missense variant within the WT1 gene was identified in patient 19, diagnosed with EM, EM-related infertility, and severe dysmenorrhea." (PMID 37626618, 2023). "Reproductive phenotype was primarily observed in homozygous mutant mice except for Nf1, Rad51C, and Wt1, whereby heterozygous mutant males present the sub- or infertility." (PMID 40060932, 2025). "However, autosomal dominant monogenic mutations can also precipitate a state of infertility including SYCP3 (Synaptonemal complex protein 3), NR5A1 (nuclear receptor subfamily 5 group A member 1) and the WT1 (Wilms' tumor 1) gene." (PMID 33101214, 2020).
invasive ductal carcinoma (5 papers, 2013 to 2025). "Then, we analysed the expression of WT1 in 46 cases of ductal adenocarcinoma by IHC staining." (PMID 31845546, 2020). "They observed frequent promoter hypermethylation of BRCA2, CDH13, MSH6, PAX5, PAX6, and WT1 genes in both DCIS and adjacent invasive ductal adenocarcinoma lesions." (PMID 40131297, 2025). "To better understand the mechanisms of the SDC1 expression in invasive ductal carcinoma, we studied the correlations between SDC1 expression and related gene expressions (RSPO1, WNT1, WT1, and P16)." (PMID 24373193, 2013). "Using 100 cases of invasive ductal carcinoma tissue, we screened expressions of RSPO1, WNT1, WT1, P16, and SDC1 using immunohistochemistry." (PMID 24373193, 2013).
lymph node metastasis (5 papers, 2013 to 2024). "Additionally, we found that WT1 expression was associated both with lymph node metastasis and tumor stage." (PMID 23936312, 2013).
malignant pleural mesothelioma (5 papers, 2009 to 2024). A malignant neoplasm that arises from mesothelial cells in the pleura and shows a diffuse growth pattern. "We report that ONX-0914, a selective inhibitor of the immunoproteasome LMP7/β5i, enhanced the immunogenicity of malignant pleural mesothelioma cells against WT1-specific T cells." (PMID 39116074, 2024). "In addition, it can also provide sufficient materials from forceps biopsy specimens to perform most histological tests including immunohistochemical staining of that for calretinin, WT1, cytokeratin 5/6, and D2-40 in a patient with malignant pleural mesothelioma." (PMID 19536345, 2009). "The malignant pleural mesothelioma cell line ACC-MEOS-4 (MESO-4) expresses high levels of MHC-I and Wilms tumor 1 (WT1) tumor antigens." (PMID 39116074, 2024).
nephritis (5 papers, 2016 to 2024). Inflammation of renal tissue. "Indeed, the podocyte injuries caused by the induction of anti-Thy 1.1 nephritis were evaluated in the present study not only by the amount of albuminuria/proteinuria, but also by the expression of WT-1, podocin, and desmin." (PMID 32478392, 2020). "Furthermore, Gdf15-/- mice with anti-GBM nephritis exhibited a decreased number of WT1 positive podocytes in the glomeruli." (PMID 32977372, 2020). "However, NTS administration to Tmsb4x−/y mice significantly reduced the number of WT1+ glomerular tuft cells compared with Tmsb4x+/y mice with NTS nephritis (P < 0.001)." (PMID 27575556, 2016).
pancreatic ductal adenocarcinoma (5 papers, 2020 to 2025). An infiltrating adenocarcinoma that arises from the epithelial cells of the pancreas. "Wilm's tumour‐1 (WT1) is overexpressed in pancreatic ductal adenocarcinoma (PDAC) and enhances metastasis." (PMID 31845546, 2020). "The chemoimmunotherapy regimen, including WT1-DC vaccine, potently activates WT1-specific immunity in unresectable advanced pancreatic ductal adenocarcinoma patients, potentially remodeling the tumor microenvironment to facilitate conversion surgery and improve clinical outcomes." (PMID 40868263, 2025).
pancreatitis (5 papers, 2011 to 2025). Inflammation of the pancreas. "Caerulein-induced pancreatitis in these mice partially rescues glandular tissue by causing de novo Wt1 expression in PSCs, even when Wt1 is deleted from MCs." (PMID 36233262, 2022). "The proposed resolution was found suitable as the present work evaluates wT1 in the pancreas regions in the context of metabolic changes originated by pancreatitis." (PMID 40048132, 2025). "We observed that pharmacological induction of pancreatitis in normal mice provokes de novo expression of WT1 in pancreatic stellate cells, concomitant with their activation." (PMID 30763305, 2019). "As expected, three weeks after caerulein treatment of the Wt1Cre;R26REYFP mice, the pancreas was fully recovered from the induced pancreatitis and showed normal expression levels of WT1, RALDH2 and PSC markers." (PMID 30763305, 2019). "Then, we induced pancreatitis in mice where WT1 had been previously deleted, and the upregulation of WT1 in PSC partially rescued the repairing phenotype of the PSC and reduced the disorganization of the acinar tissue." (PMID 30763305, 2019). "When pancreatitis was induced in mice after WT1 ablation, pancreatic stellate cells expressed WT1 and became activated, leading to a partial rescue of the acinar structure and the quiescent pancreatic stellate cell population after recovery from pancreatitis." (PMID 30763305, 2019). "When we provoked a pancreatitis in the Wt1-lineage tracing model Wt1Cre;R26REYFP, WT1 was strongly expressed not only in the mesothelium but also in PSC." (PMID 30763305, 2019). "Pancreatitis involves inflammation of the pancreatic tissues and in Wt1-mutant mice we observed a low-grade inflammation in much of the pancreas and scattered foci of more severe active inflammation." (PMID 22216009, 2011). "When pancreatitis was induced in mice after WT1 ablation, pancreatic stellate cells expressed WT1 de novo and became activated, leading to a partial rescue of the acinar structure and the quiescent pancreatic stellate cell population after recovery from pancreatitis." (PMID 31137700, 2019). "Thus, caerulein-induced pancreatitis activates PSC even when WT1 has been previously deleted from the mesothelium." (PMID 30763305, 2019). "Thus, the induced pancreatitis in mice with deletion of WT1 and the subsequent de novo expression of WT1 in PSC partially rescued the acinar organization and, importantly, a portion of the quiescent PSC population after recovery from pancreatitis." (PMID 30763305, 2019). "Thus, most quiescent PSC derive from WT1-expressing cells after pancreatitis." (PMID 30763305, 2019). "Although the pathology of our model shares many similarities to pancreatitis mouse models, there was no elevation of serum amylase level in the Wt1-mutant mice." (PMID 22216009, 2011). "Since we have observed that caerulein-induced pancreatitis provoked de novo WT1 expression in the pancreatic stroma, and particularly in PSC, we checked the effect of this treatment in mice with conditional deletion of WT1 that normally would develop a severe pancreatic disorganization." (PMID 30763305, 2019).
pleural mesothelioma (5 papers, 2022 to 2024). A neoplasm that arises from the mesothelial cells of the pleura. "The immunohistochemical MTVT profile is similar to that of pleural mesothelioma, including the expression of calretinin, WT1, and D2-40; MTAP and BAP-1 expression may be lost." (PMID 39682143, 2024). "Immunohistochemically, these tumors exhibit similarities to pleural mesotheliomas with diffuse positivity for CK7, Calretinin, and WT1." (PMID 38409016, 2024).
vascular neoplasm (5 papers, 2017 to 2025). A benign, intermediate, or malignant neoplasm arising from vascular tissue including arteries, veins, venous sinuses, lymphatic vessels, arterioles and capillaries. "Cytoplasmic WT1 positivity is characteristic for normal endothelial cells and can be observed in many benign vascular tumors." (PMID 32671676, 2020). "WT1 positivity of the endothelial cells and the accompanying pericytic cells raises the question whether the initially reactive endothelial proliferation may transform into a true benign vascular tumor." (PMID 32671676, 2020). "However, arguing against a reactive process, Wilms tumor 1 (WT1) immunoreactivity, which is seen in many vascular neoplasms, has also been seen in a majority of EH cases." (PMID 39998691, 2025).
Alport syndrome (4 papers, 2018 to 2023). A rare renal disease characterized by glomerular nephropathy with hematuria progressing to end-stage renal disease (ESRD), frequently associated with sensorineural deafness, and occasionally with ocular anomalies. "We found that metformin or losartan protected Col4a5 G5X Alport syndrome mice against Alport syndrome-induced podocyte loss, which was evaluated by staining with the podocyte marker WT1." (PMID 33782421, 2021). "We found there were no clinical features of Alport syndrome not only in six probands with c.2858G>T(p.(G953V)) in COL4A5 plus pathogenic variants in other genes (e.g., WT1, ADCK4, NPHP1, TRPC6, COL4A4, and PAX2) but also in another six probands with only the c.2858G>T(p.(G953V)) variant." (PMID 31576025, 2020).
cardiac ischemia (4 papers, 2021 to 2024). "After cardiac ischemia, WT1 expression is reactivated in the adult epicardium, potentially generating new coronary vasculature and cardiomyocytes." (PMID 38929778, 2024). "A mouse model of cardiac ischemia/reperfusion (I/R) injury revealed that after 7 days Wt1, Tcf21, and Tbx18 were expressed in distinct as well as in overlapping populations within the subepicardial mesenchyme." (PMID 34631842, 2021). "Most importantly, we demonstrated that injury-responsive gene, WT1, was linked to upregulation of IL-6, which in turn mediated the regenerative activity of ADSC via promoting cardiac dedifferentiation at the onset of cardiac ischemia." (PMID 35101092, 2022). "Wt1 was found to be induced by hypoxia-inducible factor 1a (HIF1a) in ECs, which could explain its reactivation after cardiac ischemia, but not after pressure-overload." (PMID 34631842, 2021).
clear cell renal cell carcinoma (4 papers, 2010 to 2016). "Wilms Tumor 1 (WT1) downregulates hTERT transcription in clear cell renal cell carcinoma (ccRCC) by directly binding to hTERT promoter or by repressing c-Myc expression via its promoter activity." (PMID 27548225, 2016). "We performed sequencing analysis on all 10 exons of the WT1 gene in a total of 182 patients with clear cell renal cell carcinoma (ccRCC)." (PMID 23484026, 2013). "WT1 and its target gene human telomerase reverse transcriptase (hTERT) were analysed in clear cell renal cell carcinoma (ccRCC)." (PMID 20842112, 2010). "WT1 is not expressed in the adult kidney, but shows elevated expression in clear cell renal cell carcinoma (ccRCC)." (PMID 25025131, 2014).
Hernia (4 papers, 2022 to 2025). "The strongest association was observed at 2p16.1 (EFEMP1), closely followed by 1q41 (ZC3H11B) and 11p13 (WT1) which were all identified as shared susceptibility loci on analysis of the individual hernia cohorts." (PMID 36584111, 2022). "To our knowledge, this study also represents the first GWAS of hiatus hernia in which we identified eight susceptibility loci of which four loci (2p16.1 (EFEMP1), 6p22.2 (BTN2A1), 7q33 (CALD1), 11p13 (WT1) are known to correlate with abdominal hernia." (PMID 36584111, 2022). "Five biologically relevant loci were discovered on individual hernia analyses to confer shared susceptibility to multiple hernia phenotypes including 1q41 (ZC3H11B), 2p16.1 (EFEMP1), 6p22.1 (MHC region), 7q33 (CALD1) and 11p13 (WT1)." (PMID 36584111, 2022). "This is an internal control to confirm the deletion of WT1 and indicates that hernia was healed by CS1 and that the observed decrease on CDH was not due to a deficient deletion of the WT1 gene in those animals treated with CS1." (PMID 39425191, 2024).
male infertility (4 papers, 2013 to 2025). The inability of the male to effect fertilization of an ovum after a specified period of unprotected intercourse. "Loss of function of WT1 in Sertoli cells (Amh-Cre induced) caused male infertility phenotype with testicular cords disruption, and basal lamina fragmentation occurred as early as at E15.5 testes 34, which is much earlier than Amh-Cre-cKO males in this study." (PMID 34815802, 2021). "Our data indicate that WT1 mutation is one genetic cause of male infertility and suggest that WT1 mutational analysis will be useful for diagnosis in a clinical setting." (PMID 23935527, 2013). "Such disruption of the BTB is also known to result in germ cell loss and male infertility in humans, and our observation of WT1 mutations in NOA patients strongly suggests that altered WT1 function constitutes one genetic cause of azoospermia in humans." (PMID 23935527, 2013).
meningioma (4 papers, 2014 to 2025). A generally slow growing tumor attached to the dura mater. "- Meningiomas: WT1- Hemangiomas: VEGFR2, Endoglin (CD105)- Melanocytic nevi: MART-1, BRAF, NRAS mutations- Lipoma: HMGA2-expressing cells." (PMID 40630962, 2025). "The authors have shown that fibroblastic meningiomas were negative for WT1." (PMID 24987706, 2014). "In the current study, WT1 was negative in all the studied histopathological types of meningioma." (PMID 24987706, 2014). "The radiologically-determined location of the tumor was consistent with aggressive meningioma; however, this possibility was ruled out because the morphology was not typical of either conventional or papillary subtypes and both of these are usually negative for PAX8 and WT1." (PMID 29960592, 2018).
Ovarian Insufficiency (4 papers, 2015 to 2023). "Deficiency of WT1, a sex-determining gene, induces ovarian insufficiency in humans through the regulation of granulosa cell differentiation during follicle development." (PMID 36982971, 2023). "Some showed masculinization with normal fertility while others had POI‐like phenotypes, indicating that characterization of different WT1 variants is important in genetic analysis of females with ovarian dysfunction." (PMID 34845858, 2022). "Moreover, variants in the Wt1 gene in animals are associated with ovarian insufficiency." (PMID 34845858, 2022).
ovarian serous tumor (4 papers, 2019 to 2023). A benign, borderline, or malignant epithelial tumor of the ovary characterized by the presence of neoplastic epithelial cells that, in well differentiated tumors, resemble the epithelial cells of the fallopian tube and, in poorly differentiated tumors, show anaplastic features. "For example, more than 90% of serous ovarian tumors are positive for WT1, and its presence has been shown to be specific enough to distinguish serous ovarian tumors from those of other cellular origin." (PMID 36138335, 2023). "First, we measured the expression of the uterine-associated transcription factor HOXB6, and the UCEC serous ovarian tumor biomarker WT1 in SK-OV-3, in the OV cell line Caov-4, and in the UCEC cell line HEC-59." (PMID 33926541, 2021). "PAX8 is expressed in ovarian and endometrial neoplasias, whereas WT1 is expressed in ovarian serous tumors and is useful to support ovarian origin." (PMID 31807285, 2019). "Within pathology, WT-1 protein expression is considered as a serous differentiation marker since it is positively expressed in many ovarian serous tumors including LGSC." (PMID 30949203, 2019). "The results were further validated by selected proteins of OVGP1, WT-1, and FOM3, which were highly expressed in the samples of the fallopian tube, ovarian epithelial inclusions, and ovarian serous tumors, but not in ovarian surface epithelia." (PMID 30949203, 2019).
parathyroid cancer (4 papers, 2021 to 2025). "Pathogenic CDC73 mutation is suspected to cause parathyroid cancer, and the WT1 variant could be an incidental finding from NGS." (PMID 35586626, 2022). "A deeper analysis of gene expression and functional prediction suggested that Wilms tumor 1 (WT1) is a potential biomarker for CDC73-mutant parathyroid carcinoma, which was further validated through immunohistochemistry." (PMID 37121965, 2023). "We tested the feasibility of using WT1 as a single-gene biomarker for CDC73-mutant parathyroid carcinoma." (PMID 37121965, 2023). "One patient with a WT1 variant (c.1139G>A [p.Arg380Gln]), reported as VUS, had a pathogenic CDC73 mutation (c.376C>T [p.Arg126Ter]) and was diagnosed with parathyroid cancer." (PMID 35586626, 2022). "In our previous study, we suggested that WT1 may be a potential marker for CDC73-mutant parathyroid cancer." (PMID 40434298, 2025). "In addition, the tumor of patient 9 stained positive for WT1, a novel IHC marker for CDC73-mutated parathyroid cancer as suggested in our previous study." (PMID 40434298, 2025). "In addition, immunohistochemical (IHC) staining of WT1 in 38 parathyroid tissues (28 adenomas, 4 CDC73WT carcinomas, and 6 CDC73Mut carcinomas) confirmed the presence of CDC73Mut–specific WT1 in parathyroid cancer tissues." (PMID 37121965, 2023). "Additionally, four patients with parathyroid cancer had VUSs: two APC variants (c.5378C>G [p.Ala1793Gly] and c.890C>T [p.Thr297Ile]), one WT1 variant (c.1139G>A [p.Arg380Gln]), and one PRKAR1A variant (c.567A>C [p.Glu189As])." (PMID 35586626, 2022).